CD44 (CD44 molecule (IN blood group))
Diseases named in the same sentence as CD44 in open-access papers (continued):
Sharing a sentence is not in itself a finding about the gene and the disease.
breast carcinoma (continued). "HACSLA-NPs also showed high cellular internalization via CD44 receptors, quick drug release inside the cells, and amended cytotoxicity against positive CD44 BT-20 breast cancer cell line as opposed to negative CD44, Michigan Cancer Foundation-7 (MCF-7) cell line." (PMID 32151062, 2020). "Similarly, reduced E-cadherin and CD24 and increased vimentin, CD44, and Snail were also observed in MDA-MB-468 cells – another PTEN-negative breast cancer cell line with a 44-bp deletion in the PTEN gene, which results in frameshifting and loss of the PTEN protein 18,52." (PMID 32728066, 2020). "Given that SRp55 is commonly mutated in breast and colorectal cancers, and influences the alternative splicing patterns of several tumor-associated genes like KIT, CD44, and FGFR1, it is not surprising that SRp55 depletion decreased the invasion of breast cancer cells." (PMID 32756405, 2020). "However, in the tumor cells from Her-2 positive breast cancer patients after treatment with lapatinib, there was no significant increase of CD44+CD24− phenotype cells." (PMID 31300015, 2019). "In patients treated with neoadjuvant letrozole, CD44+/CD24− mammosphere forming cells, representative of CSCs, were increased and the remaining tumour cells appeared to have a mesenchymal phenotype consistent with the more aggressive, basal-like type of breast cancer." (PMID 30975104, 2019). "When tumor cells from the Luminal-A breast cancer subtype were exposed to TME-enriched conditions consisting of TNFα and endothelial growth factor (EGF), the breast cancer cell population became enriched for a CD44+CD29+ CSC phenotype with increased metastatic properties." (PMID 31450577, 2019). "These analyses reveal that in contrast to TGFβ, rhPRG4 leads to reduction in the protein abundance of CD44 and HAS2 in the absence or presence of exogenous TGFβ, which could provide a mechanism by which rhPRG4 suppresses TGFβ-induced invasiveness of breast cancer cells." (PMID 31361756, 2019). "Also, TGF-beta converted CD44− non-cancer stem cells (CSCs) into undifferentiated CD44+ CSCs in colorectal cancer, and IL-6 and IL-8 were important to maintain aggressive traits of breast cancer cells." (PMID 30989585, 2019). "Our in vitro experiments showed that IBC could attenuate 17β‐estradiol (E2)‐induced paclitaxel resistance and that E2 could stimulate CD44 expression in ER+ breast cancer cells but not in ER− cells." (PMID 30179299, 2018). "Interestingly, EMT-type CSCs (CD44+) are associated with low SIRT7 and share similar set of genes with OCT3/4, suggesting differential roles of Sirtuins on breast cancer stemness: SIRT1 is related to MET-type CSCs (ALDH1+), whereas SIRT7 is correlated with EMT-type (CD44+)." (PMID 30038266, 2018). "Forty two pairs breast cancer and matched adjacent tissues were stained with ALDH1 or CD44 antibody in each test, to detect the potential stem cells, and results showing that the intensities of either ALDH1 or CD44 was much stronger in cancer tissues than that of adjacent tissues." (PMID 29262559, 2017). "We observed the selective packaging of P-gp, CD44, Ezrin, Radixin, and Moesin in MDR breast cancer derived MPs together with 117 other proteins unique to the resistance cargo, which we proposed may play a role in establishing the MDR phenotype in cancer cell populations." (PMID 29062386, 2017). "Moreover, subcutaneous injection of ACTN4-expressing CD44+/CD24− cells resulted in an increased incidence of tumor formation, even when only 1000 cells were implanted, further verifying the tumorigenic significance of ACTN4 on breast cancer." (PMID 29197410, 2017). "Thus, we concluded that DACH1 might exert inhibitory effects on the development of breast cancer partly by suppression of EMT inducers and CSCs markers, especially CD44." (PMID 28659634, 2017).
breast carcinoma (continued). "The expression of ALDH1 alone or with the expression of cell surface markers CD44 or CD133, has been used to enrich a cell population with chemoresistant and stem-cell like properties in head and neck squamous cancer cells, lung, colon cancer and in breast cancer." (PMID 28881734, 2017). "In this paper, we have mentioned some genes may be used as potential targets for treating breast cancer including KLF6-SV1, CD44, VEGF121b, VEGF165b, VEGF-A, FGFR1, hnRNP A1, A2, I and hnRNP K. Among of them VEGF series variants have the more possibility to be used in the clinical practice." (PMID 28881705, 2017). "For in situ characterization of breast cancer stem cells, we did not use the combination of markers CD44+CD24−/low, since this combination of positive and negative markers, currently used in cytometry, is more difficult to translate into in situ tissue analyses and cell counts." (PMID 28445132, 2017). "Interestingly, MET was suggested to contribute to the putative metastasis-initiator circulating cells in breast cancer (e.g. EPCAM+CD44+CD47+MET+ CTCs, but not the bulk EPCAM+ CTCs)." (PMID 28212540, 2017). "Breast cancer stem cells express high CD44 and are negative for CD24." (PMID 27029061, 2016). "However, MDA-MB-231 cells are mesenchymal-like breast cancer cells, and majority of them express high levels of CD44 protein and are CD24 negative." (PMID 26973433, 2016). "Indeed, paclitaxel treatment of MCF7 cells for 7 days resulted in an increase in the so called “side population” of cells that exclude the dye Hoechst 33342 and results in a ten-fold increase in the CD44+CD24low population of SKBR3 and MCF7 breast cancer cells." (PMID 26595803, 2016). "However, recent evidence suggests BCSCs may exist in two distinct states, mesenchymal-like (CD44+/CD24-) and epithelial-like (ALDH+), which can interconvert in breast cancer." (PMID 27285982, 2016). "While exact methods of identifying of these mammary stem cells is still debated, many agree that high CD44 expression, low CD24 expression, low CD49f expression, and the ability to form mammospheres are excellent indicators of individual mammary stem cells and potentially breast cancer stem cells." (PMID 27542214, 2016). "The presence of CD44 only in resistant breast cancer cell-derived EVs and not in resistant leukemic-derived EVs may relate to this phenomenon." (PMID 26938523, 2016). "To test whether co-treatment with tamoxifen and DCA inhibits breast cancer stem-like cells, we performed flow cytometry analysis to estimate the proportion of stem-like cell subpopulation in MCF7 cells based on the expression CD44." (PMID 27494858, 2016). "Therefore, we hypothesized that reduced levels of CD44 are responsible for the WNT5A-mediated reduction in the migration and invasion of breast cancer cells." (PMID 27623766, 2016). "Interestingly, CD34 and CD44 are also known as cancer stem cell markers, which are unique for specific types of cancer, for example, CD34 in leukemia and sarcoma, whereas CD44 in colon and breast cancer." (PMID 27066458, 2016). "Moreover, the CD44+/CD24−/low phenotype reputedly distinguishes tumorigenic from non-tumourigenic breast cancer cells." (PMID 25888636, 2015). "For example, tetracycline-regulated induction of CD44s in MCF-7 cells in vivo increases their dissemination of breast cancer cells to the liver while CD44 enrichment has been detected in estrogen receptor (ER)-negative breast cancer cells that have disseminated to regional lymph nodes." (PMID 25888636, 2015). "Likewise, CD44 is not expressed in normal breast tissue but is expressed in 80% of metastatic breast cancer." (PMID 26299618, 2015). "Moreover, the IL-6/STAT3/JAK2 pathway is involved in the maintenance of stem cell–like cancer cells because CD44+CD24+ and CD44+CD24− breast cancer cells have high phospho-STAT3 via their expression of genes such as IL6, PTGIS, and HAS1, which activate an autocrine loop." (PMID 26515594, 2015).
breast carcinoma (continued). "And last but not least, also functional CD44 might be involved in breast cancer metastasis, representing a ligand for E-selectin, pointing again toward a role for CD44 in cell adhesion and motility." (PMID 26528431, 2015). "The interaction between hyaluronan and CD44 activates the stem cell marker Nanog, Stat-3-mediated MDR1 gene expression, and ankyrin-regulated multidrug efflux in breast and ovarian tumor cells, and it can also lead to Bcl-2 expression and chemoresistance in breast cancer cells." (PMID 25605243, 2015). "Furthermore, in Id1-overexpressing MCF7 luminal type breast cancer cells, the CD44+/CD24−/ESA+ breast CSC population was enriched, whereas short hairpin RNAs (shRNAs)-mediated Id1 knockdown in MDA-MB-231 basal-like type breast cancer cells reduced the size of this population." (PMID 25938540, 2015). "Treatment with an anti-CD44 mAb strongly decreased HA-coated nanoparticle-induced cell cytotoxicity in MDA-MB-231 cells, but no obvious effects were noted in CV-1 cells, suggesting that activated CD44 mediates the increase in breast cancer cell selective cytotoxicity." (PMID 25909172, 2015). "Importantly, the same miRNAs were downregulated in CSCs from clinical breast cancer samples (lin-/CD44+/CD24-) compared to their non-tumorigenic counterparts." (PMID 25774169, 2015). "Levels of HOTAIR have been reported to be fourfold higher in colon and breast cancer stem cell-like cells (CD133+/CD44+) compared to non-stem cell-like cells (CD133−/CD44−), and its down-regulation reduced the number and size of colonies assessed by anchorage-independent growth." (PMID 24971229, 2014). "However, CD44+/CD24-/low/ESA+ does not constitute a universal antigenic phenotype of TICs in all breast cancer subtypes." (PMID 25216750, 2014). "Thus, there are possibilities that Alu and LINE-1 hypomethylation may be different according to breast cancer subtype or CD44+/CD24− and ALDH1+ breast cancer stem cell (BCSC) phenotypes." (PMID 24971511, 2014). "Thus, repression of CD44 and MMP9 by the inhibition of NF-κB could be responsible for the decreased invasiveness seen in breast cancer cells." (PMID 25184276, 2014). "Although the details of the functions of each exon in breast cancer biology are not clear, these results suggest that the functional diversity of CD44 would be due to the structural diversity of the molecule as a result of splicing by tumor-host microenvironments." (PMID 24586375, 2014). "In this study we investigated matrix hyaluronan (HA)-CD44 (a primary HA receptor) interaction with c-Jun N-Terminal Kinase (JNK)/c-Jun signaling in MDA-MB-468 breast cancer cells [a triple-negative (estrogen receptor-negative/progesterone receptor-negative/HER2-negative) breast cancer cell line]." (PMID 24606718, 2014). "Taken together, these findings strongly suggest that the HA/CD44-mediated JNK/c-Jun signaling pathways and miR-21 function represent new treatment targets to force tumor cells to undergo apoptosis/death and to overcome chemotherapy resistance in breast cancer cells." (PMID 24606718, 2014). "It was reported that CD44+ progenitor-like cells of normal mammary epithelium were globally hypomethylated compared to luminal epithelial (CD24+ and MUC1+) and myoepithelial (CD10+) cells and cell type-specific methylation patterns were conserved in breast cancer." (PMID 24971511, 2014). "In an attempt to identify novel antigens that may be combined with CD44 and CD24 to specifically sort TICs, we compared the expression of a panel of surface antigens between the CD44+/CD24-/low and CD44+/CD24+ cell subpopulations of three basal A or B breast cancer cell lines." (PMID 25216750, 2014). "However, further studies suggested that CD44+/CD24−/low feature alone is not enough for the spread of breast cancer pointing to the existence of additional markers to define potential breast CSCs." (PMID 23990015, 2014).
breast carcinoma (continued). "However, several markers, including CD133, CD24, CD44, CD166, EpCAM (CD326), CXCR4 (CD184), c-kit (CD117), and among others have been identified as surface markers of CSCs isolated from glioblastoma, breast cancer, pancreatic cancer, prostate cancer, or hepatocellular carcinoma." (PMID 24675390, 2014). "However, CD44+/CD24-/low/ESA+ is not a universal marker phenotype of TICs in all breast cancer subtypes." (PMID 25216750, 2014). "Importantly, CXCR4 mRNA was higher in stem cell-enriched CD44+ /CD24− - patient-derived breast cancer cells compared to non-enriched cells." (PMID 24583601, 2014). "CSCs have been identified and isolated from various tumors using specific cell surface markers, including CD44 for head and neck cancer, CD133 for prostate cancer, CD90 for liver tumor, CD24 for ovarian cancer, CD133 for brain tumor, CD44+CD24−/low for breast cancer, and CD133 for lung cancer." (PMID 24955581, 2014). "CD49f and SSEA4 along with other surface markers, such as CD24, CD44, CD133, have been commonly used for the detection of CSCs in solid tumors, including human breast, brain, colon, and ovarian cancer, as well as for categorizing breast cancer molecular subtypes." (PMID 23761858, 2013). "However, the biological role of CD44 repression by BXL0124 in breast cancer has not been fully explored." (PMID 23326564, 2013). "Due to its ability to target breast cancer stem-like cells and bulk MDA-MB-231 (triple-negative, basal-like) and SUM-159 (triple-negative, mesenchymal) breast cancer cells from ALDH+ and ALDH+/CD44+/CD24− tumor initiating subpopulation, LLL12 is a therapeutic candidate." (PMID 24376586, 2013). "Here, we identify two T-ISC subsets within this population in triple negative breast cancer (TNBC) lines and dissociated primary breast cancer cultures: CD44+CD24low+ subpopulation generates CD44+CD24neg progeny with reduced sphere formation and tumourigenicity." (PMID 23982961, 2013). "CD44 (isoform 10) was found to be selectively present on the breast cancer-derived MPs and not on leukaemic MPs and may contribute to the observed selective transfer of P-gp to malignant breast cells observed." (PMID 23593486, 2013). "Very recent data suggest that the standard isoform of CD44 mRNA (without splicing inclusion of its variable exons) might in fact play a key role in metastatic breast cancer, particularly in enabling an epithelial-mesenchyme transition of breast cancer cells." (PMID 23935626, 2013). "Interestingly, an exposure of non-adherent human metastatic MDA-MB-231 and BCM2 breast cancer cells to three cycles of hypoxia and re-oxygenation has also been observed to be accompanied by an enrichment of the CD44+/CD24−/low/ESA+ BCSC fraction." (PMID 23301832, 2013). "However, in samples from patients with tumor recurrence or metastasis, the proportion of CD44+/CD24- tumor cells was significantly higher in breast cancer tissue with basal-like features than in tissue without such features (22.66% versus 17.70%, p = 0.05)." (PMID 22762532, 2012). "Furthermore, the presence of CD24−/CD44+ or CD24+/CD44+ cells in primary tumors did not correlate with the overall or metastasis-free survival of breast cancer patients." (PMID 23042145, 2012). "In addition, we identified a tumorigenic signature of 493 differentially expressed genes comprising the overlap of two enriched tumor-initiating cell populations (CD44+/CD24−/low vs. bulk tumor cells and mammospheres vs. primary tumor) using biopsies obtained from women with primary breast cancer." (PMID 22879872, 2012). "Moreover, breast cancer stem cells are characterized by the low or negative expression of CD24 but the high expression of CD44." (PMID 23300877, 2012). "Similarly, in human breast cancers, tumor suppressor miRNA let-7 which inhibits self-renewal capacity and promotes differentiation by repressing H-Ras and high mobility group AT-hook 2 (HMGA2)was found to be downregulated in the CD44+/CD24−/low BCSCs." (PMID 24977105, 2012).
breast carcinoma (continued). "Breast cancer cell enrichment for CD44 did not significantly affect the capacity of the tumor cells to be reprogrammed; however proliferation in-vivo appears to be decreased in the CD44-depleted chimeras." (PMID 23155468, 2012). "Because the significance of CD44+/CD24- is probably not unique to breast cancer, and CD44 has been highly expressed in gastric cancer, we might speculate that similar or other molecules may also regulate the process of recurrence for gastric cancer." (PMID 22839505, 2012). "However, the genetic mechanism that leads to a high level of CD44 expression in breast cancer cells and BCSCs is not well understood." (PMID 23226410, 2012). "A total of 22 WT mice were used, of which 16 received lung tissue cells from MMT mice, three WT mice received lung tissue cells collected from MUC1.Tg mice as negative controls, and three WT mice were injected with CD44+ tumor cells sorted from primary MMT mammary tumors, as positive controls." (PMID 22277639, 2012). "Application of an ATM inhibitor effectively decreased the radiation resistance of CD44+/CD24−or low subset, suggesting that targeting ATM signaling may provide a new tool to eradicate stem-like CIC and abolish the radiation resistance of breast cancer." (PMID 21935375, 2011). "To determine whether the dormant breast cancer cells expressed known breast cancer stem cell markers we performed immunofluorescence for aldehyde dehydrogenase 1 (ALDH1) and cluster of differentiation 44 (CD44) on FTI-treated MCF-7 cells." (PMID 22046561, 2011). "Furthermore, studies have indicated that human breast cancers and cell lines contain a sub-population of cells characterised by CD44+/CD24−/low/Lin− cell surface markers, and a partial overlap between CD44+/CD24−/low/Lin− and ALDH1-positive populations was reported." (PMID 20010944, 2010). "While, the proportion of CD44+/CD24- cells did not correlate with gene expression-based classifiers of breast cancer subtype, consistent with previous reports, there was a striking relationship between the proportion of CD44+/CD24- cells in the line and spindle-cell morphology." (PMID 20964822, 2010). "In contrast to CD44 expression, not all breast cancer cell lines contained CD24+ cells." (PMID 20964822, 2010). "Since our observation of increased SLUG expression in CD44+/CD24- cells originated from a cell line study, we first examined the gene expression array data available in NCBI GEO omnibus to correlate SLUG expression with CD44+/CD24- status of primary breast cancers." (PMID 20691079, 2010). "Notably, a very recent study has shown that cytotoxic chemotherapies including an anthracycline and taxane increased the proportion of ALDH1-positive breast cancer cells but not that of CD44+/CD24- breast cancer cells." (PMID 20959018, 2010). "Although there remains a need to determine whether CD44+/CD24-/low cells are true breast cancer stem cells across all the various breast cancer subtypes, there seems to be a connection between EMT and CD44/CD24 expression in the mechanisms of breast cancer invasion and metastasis." (PMID 20696077, 2010). "In a recent study related to our work, an identical epigenetic state in the promoter region of the CD24 gene has been observed between interconvertible CD24-positive and negative subsets of CD44+ breast cancer cells, indicating that transcriptional permissiveness is a general phenomenon." (PMID 20730114, 2010).